HAUS5 (HAUS augmin like complex subunit 5)
Description:
Contributes to mitotic spindle assembly, maintenance of centrosome integrity and completion of cytokinesis as part of the HAUS augmin-like complex.
Synonyms: KIAA0841; dgt5
Tractability: PROTAC: ubiquitination databases record sites on it; its protein half-life has been measured.
Gene: Protein-coding gene on chromosome 19 (35,612,735 to 35,625,355, forward strand). Ensembl gene ENSG00000249115.
Subcellular location: Cytoplasm, cytoskeleton, microtubule organizing center, centrosome; Cytoplasm, cytoskeleton, spindle
Pathways (Reactome):
Cell Cycle: AURKA Activation by TPX2; Loss of Nlp from mitotic centrosomes; Loss of proteins required for interphase microtubule organization from the centrosome; Recruitment of NuMA to mitotic centrosomes; Recruitment of mitotic centrosome proteins and complexes; Regulation of PLK1 Activity at G2/M Transition
Organelle biogenesis and maintenance: Anchoring of the basal body to the plasma membrane
Gene Ontology:
Molecular function: protein binding
Biological process: centrosome cycle; spindle assembly; regulation of microtubule nucleation
Cellular component: centrosome; HAUS complex; mitotic spindle microtubule; cytosol; spindle
Genetic constraint (gnomAD): Loss-of-function variants: 66 observed, 94.25 expected, observed/expected ratio (o/e) 0.7, 90% interval 0.57 to 0.86. The upper end of that interval is the gene's LOEUF score, 0.86, which puts it in group 3 of 6, group 1 being the genes least tolerant of losing a copy. Missense variants: 729 observed, 811.87 expected, observed/expected ratio (o/e) 0.9, 90% interval 0.84 to 0.95. Synonymous variants: 337 observed, 346.43 expected, observed/expected ratio (o/e) 0.97, 90% interval 0.89 to 1.07.
Homologues: Orthologues: chimpanzee HAUS5 (98% identical), macaque HAUS5 (95% identical), pig HAUS5 (82% identical), dog HAUS5 (82% identical), guinea pig HAUS5 (78% identical), rabbit HAUS5 (76% identical), rat Haus5 (73% identical), mouse Haus5 (71% identical).
Diseases named in the same sentence as HAUS5 in open-access papers:
HAUS5 is named in the same sentence as 20 diseases in open-access papers, as found by Europe PMC text mining. Sharing a sentence is not in itself a finding about the gene and the disease. The quoted sentences say what the papers report.
breast carcinoma (2 papers, 2022 to 2025). "Additionally, we detected multiple missense mutations in HAUS5, a gene recently implicated in breast cancer prognosis, though its specific role in ovine mammary function remains to be elucidated." (PMID 41021472, 2025). "In this study, we first found that HAUS5 mRNA overexpressed in breast cancer." (PMID 35280773, 2022). "Our study highlights the potential carcinogenic role of HAUS5 in breast cancer." (PMID 35280773, 2022). "It suggests that HAUS5 may be involved in the onset and progression of breast cancer." (PMID 35280773, 2022). "From the interaction network diagram, we can see that several oncogenes and immune-related genes directly interact with HAUS5, and many genes have been supported to be related to breast cancer, indicating that the HAUS5 gene we studied may have a very important function in breast cancer." (PMID 35280773, 2022).
liver cancer (2 papers, 2022 to 2023). An epithelial or non-epithelial malignant neoplasm that arises from the liver. "Our studies indicated that inhibition of HAUS5 expression significantly reduced the proliferation of liver cancer cells." (PMID 36765148, 2023). "In this study, the pan-oncogene HAUS5 was identified as a novel prognostic marker for liver cancer by bioinformatics analysis." (PMID 36765148, 2023). "In vitro, knockdown of HAUS5 inhibited the proliferation of hepatoma cells, highlighting the potential carcinogenic role of HAUS5 in liver cancer." (PMID 36765148, 2023). "We further verified by in vitro experiments that inhibition of HAUS5 expression suppressed the proliferation of liver cancer cells." (PMID 36765148, 2023). "Our results indicated that HAUS5 expression was closely related to the clinical parameters and development of liver cancer." (PMID 36765148, 2023).
glioma (1 paper, 2023). A benign or malignant brain and spinal cord tumor that arises from glial cells (astrocytes, oligodendrocytes, ependymal cells). "Low expression of HAUS4 and HAUS6 and high expression of HAUS1, HAUS3, HAUS5, HAUS7, HAUS8 may be risk factors for poor prognosis in glioma patients." (PMID 37161065, 2023). "The research found that expression levels of the Augmin family genes HAUS1, HAUS3, HAUS4, HAUS5, HAUS6, HAUS7, and HAUS8 was all related with survival rates of glioma patients." (PMID 37161065, 2023).
hepatocellular carcinoma (1 paper, 2023). A malignant tumor that arises from hepatocytes. "We further investigated the co-expressed genes as well as mutations in all patients with hepatocellular carcinoma and the correlation between HAUS5 expression and immune infiltrates." (PMID 36765148, 2023). "Finally, the results of in vitro experiments showed that when HAUS5 was knocked down, the proliferation of hepatoma cells was significantly decreased." (PMID 36765148, 2023). "However, the role of HAUS5 in hepatocellular carcinoma remains unknown and deserves further investigation." (PMID 36765148, 2023).
primary immunodeficiency (1 paper, 2022). "The results showed that high HAUS5 expression was mainly enriched in mitotic prometaphase, primary immunodeficiency, DNA replication, cell cycle related signaling pathways." (PMID 35280773, 2022). "mitotic prometaphase, primary immunodeficiency, DNA replication, cell cycle related signaling pathways were all enriched in the presence of elevated HAUS5 expression, according to GSEA analysis." (PMID 35280773, 2022).
tumor (4 papers, 2017 to 2023). "We explored the possible role of HAUS5 in HCC immunotherapy by ssGSEA, and we found that the expression of HAUS5 was significantly associated with the levels of most tumor-infiltrating immune cells, especially activated CD8 T cells and natural killer cells." (PMID 36765148, 2023). "Upregulated HAUS5 was associated with poor clinicopathological characteristics such as tumor T stage, ER, PR, and HER2 status." (PMID 35280773, 2022). "Knockdown of ZNF131 or HAUS5 each caused similar, profound loss of tumor formation for GSC-0131-derived xenograft tumors, where tumors growth was assayed 7 weeks post-injection." (PMID 28596487, 2017). "Therefore, the expression level of HAUS5 is related to the level of immunity and mutation of tumor cells." (PMID 35280773, 2022). "The protein expression level of HAUS5 in normal and tumor tissues was found by using clinical specimens from the CPTAC and HPA databases." (PMID 36765148, 2023). "To determine the significance of HAUS5 expression in tumor development, we observed the correlation between HAUS5 expression and pathological features of LIHC in the Kaplan‒Meier Plotter database." (PMID 36765148, 2023). "The BRCA microenvironment’s core gene, HAUS5, was shown to be related with invading immune cell subtypes and tumor cell stemness." (PMID 35280773, 2022). "HAUS5 can be used as a potential marker and deserves further analysis to explore its role in the process of tumor occurrence, development, metastasis, and differentiation associated with immune infiltration from the experimental level." (PMID 35280773, 2022). "In many cancers, the mRNA expression level of HAUS5 was significantly increased, and the tumor tissue contains not only tumor cells, but also a variety of different types of cells, such as stromal cells, fibroblasts, and immune cells, which together constitute the tumor microenvironment." (PMID 35280773, 2022). "The expression or copy number variation of HAUS5 gene will affect the tumor microenvironment and may play an important role in the occurrence, development, metastasis, and immune response of cancer." (PMID 35280773, 2022). "Abnormal expression of HAUS5 can induce microtubule fragmentation of centrosome and increment of centrosome volume, leading to chromosome dislocation and functional defects of bipolar spindle, which in turn may induce tumor formation." (PMID 35280773, 2022). "Moreover, ZNF131 and HAUS5 kd phenocopied each other in GSCs, each causing: mitotic arrest, centrosome fragmentation, loss of Augmin/HAUS complex on the mitotic spindle, and loss of GSC self-renewal and tumor formation capacity." (PMID 28596487, 2017). "We downloaded data of tumor cell lines from the CCLE database and analyzed the expression of HAUS5 in multiple tumor cells." (PMID 36765148, 2023). "The Clinical Proteomic Tumor Analysis Consortium (CPTAC) and the Human Protein Atlas (HPA) databases were used to evaluate HAUS5 protein expression." (PMID 36765148, 2023).
cancer (2 papers, 2022 to 2023). A tumor composed of atypical neoplastic, often pleomorphic cells that invade other tissues. "After confirming that HAUS5 was overexpressed in most tumors, we further explored whether HAUS5 expression was associated with prognosis in pan-cancer patients." (PMID 36765148, 2023). "HAUS augmin-like complex subunit 5 (HAUS5) is involved in the occurrence and development of various cancers." (PMID 36765148, 2023). "To explore the possible role of HAUS5 in carcinogenesis, we first analyzed the expression of the HAUS5 gene in 37 human cancers of TCGA using the TIMER database." (PMID 35280773, 2022). "Furthermore, HAUS5 was a low-risk gene in READ and THYM, while it was a high-risk gene in other types of cancer." (PMID 36765148, 2023). "The results showed that HAUS5 was significantly associated with multiple genes involved in cell division and cell cycle regulation, including MCM224, MCM525, MCM619, MCM726 and PLK127, which have been shown to play important roles in a variety of cancers." (PMID 36765148, 2023). "HAUS5 may will be a new therapeutic target into clinical practice of cancer therapy." (PMID 36765148, 2023). "The Cancer Genome Atlas (TCGA), Genotype-Tissue Expression (GTEx), Cancer Cell Line Encyclopedia (CCLE) and Gene Expression Omnibus (GEO) databases were used to analyze the mRNA expression of HAUS5." (PMID 36765148, 2023). "Pan-cancer was analyzed by TIMER2 web and the expression differential of HAUS5 was discovered." (PMID 35280773, 2022).
HAUS5 also shares sentences with these, for which no sentence is quoted: glioblastoma (2 papers); acute myeloid leukemia (1); adrenocortical carcinoma (1); cervical squamous cell carcinoma (1); Joubert syndrome (1); mesothelioma (1); ovarian serous cystadenocarcinoma (1); pancreatic adenocarcinoma (1); sarcoma (1); skin cutaneous melanoma (1); testicular germ cell tumor (1); thymoma (1); uterine carcinosarcoma (1).